DBP (D-box binding PAR bZIP transcription factor)
Diseases named in the same sentence as DBP in open-access papers (continued):
Sharing a sentence is not in itself a finding about the gene and the disease.
infection (continued). "Using the FLAG-tagged Ad constructs, we showed that during low MOI infections, the level of DBP expressed from E1-deleted Ad in A549 and HepG2 cells is very low and does not support efficient replication." (PMID 28700677, 2017). "At late infection times (24 and 30 hpi), the quantity of full-length DBP within the infected cell was very high, and several smaller FLAG-tagged protein species were also present." (PMID 28700677, 2017). "Our results show that most deletions within the C-terminus affect expression of DBP and this is particularly evident at 48 h after infection at the protein level." (PMID 29257057, 2017). "During the earliest times post-infection, the initial localization of DBP was detected in a few small nuclear foci (at 12 hpi), followed by a progressive increase in their number and size." (PMID 27819325, 2016). "For example, DBP was only readily detectable in dl520-infected cells at 48 hours after infection, with only a faint band observed at 24 hours." (PMID 26448631, 2015). "DBP is an Ad protein that is synthesized initially prior to Ad DNA replication and whose synthesis continues well into the late stage of infection." (PMID 25807051, 2015). "The localization of B23.1, B23.2, pTP and DBP was then examined by immunofluorescence at 18 h post-infection." (PMID 18024892, 2007). "At 24 hours post infection, weak DBP and E4 protein expression were detectable, but only with the E1A-HD2 virus." (PMID 17020613, 2006). "To determine whether altered levels of mRNA translate to protein expression, we performed western blotting for E1A, DBP, and the late proteins in HT and HT-A cells at 16, 24, 48, and 72 h after infection with either dl309 or dl1102." (PMID 41186411, 2025). "Levels of DBP were broadly similar between HT and HT-A cells with minimal differences throughout infection, except at 24 h in dl309-infected cells, where slightly higher levels were observed in HT-A cells compared with HT, whereas the opposite was observed in dl1102-infected cells." (PMID 41186411, 2025). "As we observed that HMGB1 can localize to RCs, we hypothesized that DBP might also interact with HMGB1, causing its relocalization during HAdV-C5 infection." (PMID 39611842, 2025). "During infection, DBP-marked replication centers recruit the cellular deubiquitinase USP7." (PMID 36095031, 2022). "Importantly, cells infected with the DBP mutant UBM5 consistently lack DBP-positive replication centers (RCs), which are usually formed during the transition from the early to the late phase of infection." (PMID 35254132, 2022). "A decrease in DBP transcripts during infection could be compensated by the observation that the protein itself seems very stable." (PMID 36366526, 2022). "Since our transcriptomic analysis predicted that E4orf6/DBP might possess late gene kinetics, we explored E4orf6/DBP expression over a time-course of infection." (PMID 36095031, 2022). "Thus, E4orf6/DBP is conserved among diverse AdV serotypes, and expressed as a true late gene during infection." (PMID 36095031, 2022). "Interestingly, E1A, the first protein expressed during HAdV infection, was expressed from 16 hpi during the entire infection cycle, along with E4orf6 and DBP in UBM5 H5pm4251-infected cells." (PMID 35254132, 2022). "At early time points postinfection, DBP diffusely localizes in the nucleus, condenses into small foci toward the end of the early stage of infection, and accumulates in spherical liquid biomolecular condensates during the late phase of infection." (PMID 35254132, 2022). "This notion might be in line with an earlier report that DBP regulates viral mRNA stability, suggesting that the DBP level is a critical determinant of infection progress." (PMID 29997215, 2018). "DBP itself was demonstrated to have significant neutrophil chemotactic activity in vivo where DBP knock-out mice demonstrated significant decreases in neutrophil recruitment to the site of infection when compared to the wild type group." (PMID 26779447, 2015).
infection (continued). "DBP served as a representative early gene product, and accordingly this protein was present at 8 hpi and accumulated to high levels during the course of the infection." (PMID 23966406, 2013). "Moreover, DBP staining was either diffuse in the cell nuclei or present in one large replication centre per cell, indicating that infection was stalled at an early stage." (PMID 21182761, 2010). "Our data show that these effects are mediated primarily through interactions with pTP and DBP, that B23.1 and B23.2 act in different replicative environments as the infection progresses and that the two isoforms have different interactions with the replicative machinery." (PMID 18024892, 2007). "Notably, a pair of E2 mRNAs, E2B IVa2 and E2A DBP, displayed a unique expression pattern that showed opposing expression regulation in the transition to the late phase of infection, where DBP mRNA was downregulated whereas E2B IVa2 was exponentially upregulated." (PMID 36366526, 2022). "As the viral replication cycle progresses and viral genome replication begins, DBP organizes in slightly larger spheroid foci and ring-like structures (from 20 to 24 hpi) that ultimately form more complex morphologies as the ring-like structures coalesce at late times of infection (28–36 hpi)." (PMID 34578359, 2021). "WT virus expressed DNA binding protein (DBP) from the E2A gene in distinctive foci within the cell nuclei that are indicative of active replication; it also expressed a high level of late proteins as expected of a normally progressing infection 20 hours post-infection (h.p.i.)." (PMID 21182761, 2010). "Human lung epithelial A549 cells were infected with AdV at high multiplicity of infection (MOI of 1.5) for 24 hours, incubated with VdU for 4 hours, fixed, labeled with AO-6MT, and stained for the VRC with DBP antibodies." (PMID 39454009, 2024). "In contrast to the transfection experiments, ubiquitination of WT DBP and UBM2 was undetectable in infections (lanes 5 and 6), but clearly detectable in infections with UBM5 H5pm4251 (lane 7)." (PMID 35254132, 2022). "We show that DBP expression and stability and viral DNA replication in UBM2 H5pm4250 infections are widely comparable to WT H5pg4100 despite the affected recruitment of USP7 into RCs at the 24-hpi time point." (PMID 35254132, 2022). "In contrast, during AdΔE4 infection, the SMARCAD1 protein exhibits striking reorganization to colocalize with DBP and BrdU at VRCs." (PMID 34463575, 2021). "The mRNA expression of early genes (E1A and DBP) and the replication of the genomic DNA was only affected when 17-AAG was added immediately after infection." (PMID 33670684, 2021). "Interestingly, expression from the viral E2 promoter showed only a minor difference between the E2-DNA Binding Protein (E2 DBP) and the E2-Polymerase (E2 Pol), with the former starting to show expression increasing between 11 and 12 hours and the latter at 12 and 13 hours after infection." (PMID 30677073, 2019). "For instance, inhibition of the classical nuclear import pathway during infection failed to disrupt DBP nuclear import; however, VRC formation was significantly impaired." (PMID 38639487, 2024). "When we performed the same assay in Vero cells, or Vero W162 cells that can complement the lack of E4orf6/7 but not E4orf6/DBP during ΔSS-infection, we again quantified a significant reduction in plaque size when comparing the WT Ad5 to ΔSS virus." (PMID 36095031, 2022). "In contrast, at 24 h and 48 h after infection with WT H5pg4100, the intensity of diffuse nuclear staining was greatly reduced, and in all of the infected cells examined (n > 140), USP7 was clearly seen concentrated in DBP-positive RCs." (PMID 35254132, 2022). "HELLS/SMARCA6 exhibits diffuse nuclear localization without obvious colocalization with DBP during infection with Ad5 WT or AdΔE4 viruses (data not shown)." (PMID 34463575, 2021).
infection (continued). "The resulting proteins could be assigned to different structural components of the virus such as the capsid (e.g., TRX2, CVC2, and SCP), tegument (e.g., DBP, PAP, and NEC2) and envelope (e.g., gB, gG, and gH) related to different time points during infection (Dataset EV6A)." (PMID 39901020, 2025). "However, upon infection with HAdV-C5 wt, NEMO is partially relocalized to the nucleus, where it colocalizes with E1B-55K within the viral replication centers (as indicated by colocalization with DBP)." (PMID 40103806, 2025). "Since the same DNA compartment was visible in HAdV5 wt infection but none of the antibodies against pV, pIX and DBP showed signal in the center of the nucleus, we hypothesized a limited antibody penetration into the LVAC." (PMID 32584886, 2020). "Conversely, no changes were seen in the expression of DBP (except for the Ad12 infection)." (PMID 25807051, 2015).
cancer (19 papers, 2014 to 2025). A tumor composed of atypical neoplastic, often pleomorphic cells that invade other tissues. "DBP is a multifunctional protein with clinical importance and has a possible role in the pathogenesis or susceptibility of different diseases like cancer, cardiovascular, autoimmune and inflammatory diseases." (PMID 35163226, 2022). "A systemic review demonstrated that a large number of chronic diseases, including cancers, have been associated with DBP variants." (PMID 33868582, 2021). "In contrast, negative (0, n = 90) to weak (1+, n = 10) staining patterns were observed throughout the FATC, Some of them showed very weak to total loss of DBP expression, and consulted the patient chart for demographic data and cancer staging." (PMID 33868582, 2021). "The DBP rs16846876 polymorphism has been also linked to serum 25(OH) D concentrations in healthy subjects, pregnant women, and cancer patients." (PMID 31640710, 2019). "Genotyping for rs7041 and rs4588 polymorphism showed that subjects with the DBP phenotype Gc1f-1f had 23–26% reduced risk of cancer incident as compared with the Gc1s-1s and Gc2-2 phenotypes." (PMID 27143969, 2016). "In conclusion, we have found the DBP phenotype 1f/1f to be associated with a reduced risk of cancer." (PMID 25993554, 2015). "If the relation between the DBP variant 1f and cancer is confirmed in other studies, determination of DBP phenotype may have clinical importance." (PMID 25993554, 2015). "In addition, the variants in the DBP gene have been implicated in cancers such as breast and prostate." (PMID 25541958, 2014). "In light of the important biological function of VDR and DBP genetic polymorphisms in cancer development and progression, we hypothesized that genetic variants of the VDR and DBP genes were associated with increased susceptibility to HBV-related HCC." (PMID 25541958, 2014). "The NO donor SNAP was conjugated to the Hf12 SBUs of Hf‐DBP‐based MOL to afford SNAP/MOL for enhanced cancer radiotherapy." (PMID 39742392, 2025). "Although DBP is an essential protein with multifunctional properties, very few studies are available on its direct contribution to cancer cell proliferation, colony formation, and migration." (PMID 33868582, 2021). "The study of DNA binding protein (DBP)-drug interactions can open a breakthrough for the treatment of genetic diseases and cancers." (PMID 32689927, 2020). "Polymorphisms of genes encoding components of the vitamin D pathway including vitamin D receptor (VDR) and vitamin D binding protein (DBP) have been widely investigated because of the complex role played by vitamin D in cancer tumorogenesis." (PMID 25541958, 2014). "We also compared DBP staining intensities in FA to cancer staging, which we found inversely correlated with staging, i.e., the weaker or no DBP staining correlated to advanced staging, whereas in EA patient samples, moderate to strong staining was observed in early staging of PTC." (PMID 33868582, 2021). "In addition, DBP also has anti-inflammatory and immunoregulatory functions, and has been identified play important roles in several chronic disease including cancers." (PMID 25541958, 2014). "Glycosylation of DBP through the combined action of a betagalactosidase and a sialidase engenders the Gc macrophage activating factor (GcMAF), the most potent activator of macrophages with an important role in immune system regulation and anti-angiogenetic activity in cancer patients." (PMID 26046356, 2015). "The data collectively reveal the opposing activities between DBP and E2F8 in the regulation of Th9 cells in cancer immunotherapy in vivo." (PMID 36241625, 2022). "Compared with the adjacent normal tissues, the expression of NR1D1, DBP, and BHLHE40 was increased, while the expression of CRY1 and CLOCK was decreased in cancer tissues." (PMID 34977153, 2021).
cancer (continued). "Among them, certain rhythm genes such as DBP, CRY2, and CIART are protective effectors for the prognosis of most cancers, whereas certain rhythm genes such as TIMELESS and SERPINE1 are risk factors for the prognosis of most cancer." (PMID 31927791, 2020). "Notably, DBP and E2F8 also differentially regulate human Th9 differentiation in vitro, suggesting a clinical implication in cancer immunotherapy." (PMID 36241625, 2022). "Regardless of the cancer types, genes such as ITGA5, SERPINE1, EIF4EBP1 are majorly associated with bad outcomes; while genes such as ALDH2, DBP, FRAT1, PDCD4 are associated with good outcomes." (PMID 35197510, 2022). "The opposing functions of DBP and E2F8, which have been reproduced and confirmed in human TH9 cells, provide potential clinical targets for the development of Th9 cell-mediated immunotherapy for human cancers." (PMID 36241625, 2022). "The expression of RBP4, SAA1, and DBP in cancer EVs was not significantly altered, compared to that in normal EVs." (PMID 33808296, 2021). "Cancer cells are believed to take up bioavailable 25-hydroxyvitamin D (25[OH]D) (i.e., not bound to vitamin-D-binding protein (DBP)) more efficiently than DBP-bound 25(OH)D." (PMID 32033150, 2020). "Other proteins, such as CLEC3B, ITIH4, SAA1, and C20ORF3 exhibited increased expression in cancer EVs, while RBP4, SAA1, and DBP did not exhibit significant differences between normal and cancer samples." (PMID 33808296, 2021).
tumor (12 papers, 2010 to 2025). "In turn, the tissue expression of DBP is likely to be associated with favorable prognostic characteristics, such as small tumor size, and low invasiveness." (PMID 36014865, 2022). "Since DBP gene variants showed differential expression across ethnicities, DBP level in the tumor microenvironment may implicate the difference in TC prognosis between Filipino and European Americans." (PMID 33868582, 2021). "On the contrary, CRY2 and DBP inhibited DNA damage and cell cycle pathways to enhance tumor cell growth." (PMID 35832846, 2022). "It is worth noting that, weak DBP expression was commonly demonstrated in aggregations of basaloid cells and peripheral cells of the tumor nodules with scanty cytoplasm that displayed the typical nuclear palisading." (PMID 36014865, 2022). "Overall, a more pronounced expression of SHH was observed in tumor cells with low expression of DBP, and vice versa." (PMID 36014865, 2022). "We have demonstrated previously in a xenograft mouse model that DBP-maf is a potent inhibitor of human pancreatic tumors and that its ability to inhibit tumor growth in vivo is due, in part, to its antiangiogenic properties." (PMID 20976141, 2010). "Real-time PCR detected the expression of E1A, Hexon, and DBP viral genomes in tumor tissue." (PMID 40459263, 2025). "In contrast, moderate to strong expression of DBP was found in differentiated tumor cells." (PMID 36014865, 2022). "Having established opposing functions for DBP and E2F8 in Th9 cell differentiation in vitro, we next determined the roles of DBP and E2F8 in Th9 cell-mediated anti-tumor activity in vivo." (PMID 36241625, 2022). "Under X-ray irradiation, Th-DBP could effectively inhibit the proliferation of CT26 tumor cells in the BALB/c mouse model, showing certain advantages over the Hf-DBP radiosensitizer material." (PMID 40733092, 2025). "This suggests that DBP and E2F8 in Th9 cells may function through regulation of Granzyme B for their anti-tumor function." (PMID 36241625, 2022). "Finally and significantly, the opposing regulatory roles between DBP and E2F8 in Th9 cells contribute to Th9-mediated anti-tumor immunity in tumor in vivo and also play an important role in human TH9 differentiation." (PMID 36241625, 2022). "Besides, the overlapping genes that exhibited similar expression levels in tumor samples from both the TCGA and ICGC databases were shown in a Venn diagram, including DBP, NPAS2, PER1, RORA, and TIMELESS." (PMID 34745328, 2021).
DBP also shares sentences with these, for which no sentence is quoted: type 2 diabetes (5 papers); multiple sclerosis (3); Parkinson’s (3); hepatocellular carcinoma (2); Insulin resistance (2); pulmonary TB (2); acute myocardial infarction (1); Allergy (1); Alzheimer disease (1); Anxiety (1); arteriovenous malformations (1); calcification (1); chronic hepatitis C (1); chronic obstructive pulmonary disease (1); chronic periodontitis (1); cognitive deficit (1); dementia with (1); digestive disease (1); genetic diseases (1); gestational hypertension (1); Glucose intolerance (1); Hypercalcemia (1); hyperparathyroidism (1); hyperphosphatemia (1); Hypertension (1); Hypocalcemia (1); Hypoglycemia (1); hypophosphatemia (1); infectious disease (1); Infertility (1).
A further 15 diseases each share a sentence with DBP in 1 paper.